TTR (transthyretin)
Diseases named in the same sentence as TTR in open-access papers (continued):
Sharing a sentence is not in itself a finding about the gene and the disease.
peripheral neuropathy (32 papers, 2011 to 2025). A disorder affecting the peripheral nervous system. "The aim of this report is to describe a case for whom peripheral neuropathy due to variant-TTR acquired from a “domino” donated liver, progressed much faster than in those who inherit a TTR mutation, and caused significant disability." (PMID 37381065, 2023). "The remaining 6 patients were genotyped as carrying an amyloidogenic TTR variant with one having peripheral neuropathy." (PMID 34722650, 2021). "Familial amyloidotic polyneuropathy (FAP) is a peripheral neuropathy caused by the extracellular accumulation and deposition of insoluble transthyretin (TTR) aggregates." (PMID 21375738, 2011). "Patrisiran was thefirst siRNA developed for ATTR amyloidosis and was FDA approved for the treatmentof hereditary TTR peripheral neuropathy." (PMID 41524065, 2025). "The significance of this in the peripheral nervous system is uncertain, since knockdown of TTR by TTR silencers for 3–5 years results in the improvement or stabilization of peripheral neuropathy in patients with ATTR." (PMID 40717228, 2025). "We describe a case of peripheral neuropathy in a White British 74 year old man with wild-type TTR, 8 years following receipt of a ‘domino’ liver transplant (from a donor with a TTR mutation)." (PMID 37381065, 2023). "A good example is ability of the polyphenol to bind transthyretin (TTR), that are protein aggregation diseases associated with peripheral neuropathy." (PMID 34298986, 2021). "TTR deposits most frequently occur in the peripheral nervous system, resulting in peripheral neuropathy." (PMID 32419519, 2020). "Tafamidis, a kinetic TTR stabilizer, was also demonstrated to slow the progress of peripheral neuropathy, and has obtained marketing authorization in Europe31." (PMID 27212199, 2016). "The TTR-FAP Registry has been planned by tertiary clinical centres for peripheral neuropathies, most of which are also members of the Italian CMT network and reference centres for acquired and genetic amyloidosis according to the guidelines of the already active French TTR-FAP Network CORNAMYL." (PMID 30286784, 2018). "Chronic alcoholism can also induce a peripheral neuropathy that is indistinguishable from TTR-FAP disease." (PMID 23425518, 2013). "In these cases, the diagnosis of ATTRv amyloid neuropathy was made from (i) performing extensive investigations to rule out other causes of small fibre neuropathy, for example, DM and (ii) using other surrogate markers (e.g., DPD scanning) as confirmation of TTR amyloid." (PMID 40580033, 2025).
cardiac disease (30 papers, 2013 to 2026). "Penetrance varies by TTR mutation, wtATTR predominantly affects the heart, and nearly 70% of AL patients develop cardiac disease." (PMID 41594160, 2026). "The aim of our study was to identify early signs of cardiac involvement in patients with a TTR gene mutation in order to differentiate carriers from patients with neurological or cardiac disease." (PMID 38132218, 2023). "Our results support an association between heart disease and P/LP TTR variants in patients ≥60 years of age, particularly in populations with high prevalence of V122I." (PMID 34746851, 2021). "We observed an effect size in the association between the TTR mutation and heart disease, similar to the one reported by a previous analysis of a general-population cohort." (PMID 30813263, 2019). "TTR amyloid deposits may be associated with wild-type TTR amyloidosis (ATTRwt), a relatively common cardiac disease of aging, but also to several TTR variants linked to hereditary cardiac and neurodegenerative amyloid diseases (ATTRv)." (PMID 36552032, 2022). "Moreover, 7 of 49 (14%) of these individuals with TTR variants aged 60 years or older had both a diagnosis of heart disease and a septal thickness ≥1.2 cm by echocardiography." (PMID 34746851, 2021). "TTR protein stabilizer, Tafamidis has been shown to have greater survival benefit when administered at earlier stages of cardiac disease." (PMID 39669619, 2024). "Pfizer’s tafamidis and its potential to stabilize amyloid cardiomyopathy (TTR) are just the tip of the iceberg in the development of pharmacological chaperones for heart disease." (PMID 26664897, 2015). "Cardiac disease penetrance and progression may be affected by a specific TTR genotype; however, the heterogeneity of genotype in our study population limits our ability to infer conclusions based on genotype." (PMID 40712265, 2025). "One of the most commonly found proteins that affect the heart disease is transthyretin (TTR)." (PMID 39841315, 2025). "NT-proBNP, troponin T, uric acid, transthyretin (TTR), and renal function are suitable serum biomarkers for risk stratification of survival in ATTRwt-CM, but they cannot differentiate ATTRwt-CM from other common cardiac diseases." (PMID 39288026, 2024). "The stability in the value of Troponin I during the study period probably could be attributed to Tafamidis in halting the progression of cardiac disease in TTR-CM patients." (PMID 34703707, 2021). "Hence, considering the findings of non-RCTs, we can associate Tafamidis with reducing cardiac disease progression in patients with TTR-CM." (PMID 34703707, 2021). "In addition to neurodegeneration, patients with TTR-FAP develop cardiac disease." (PMID 26664897, 2015). "In this group, the majority of patients had established cardiac disease on DPD scan, and three gained access to gene silencing therapy based on positive TTR amyloid on skin biopsy alone." (PMID 40580033, 2025). "TTR-related FAP (TTR-FAP; MIM #105210) has different clinical manifestations and is mainly classified as neuropathic, oculoleptomeningeal, and cardiac disease by various phenotypes." (PMID 31018485, 2019).
neurological disorders (29 papers, 2007 to 2025). "Inotersen targets the TTR mRNA to inhibit the production of misfolded hepatic TTR protein and was found in a phase 3 trial to improve the course of neurologic disease and quality of life in people with hTTR." (PMID 36678889, 2023). "A significant reduction in transthyretin levels compared to controls with other neurological disorders was found." (PMID 34573864, 2021). "Tegsedi significantly reduces the concentration of circulating TTR, which ultimately improves the course of neurologic disease and the quality of life in patients." (PMID 31117178, 2019). "The effect of tafamidis meglumine on neurological disorders, such as the frequency of transient focal neurological episodes (TFNEs), magnetic resonance imaging (MRI) findings, and TTR levels in cerebrospinal fluid, was investigated in two patients diagnosed with Y69H ATTRv mutation." (PMID 40931533, 2025). "Confirming this, dysregulations of TTR levels characterize several neurological disorders." (PMID 33919289, 2021). "This being so, TTR is extensively studied in neurological disease." (PMID 34066808, 2021). "Leptomeningeal ATTR amyloid deposits are composed of TTR protein which is synthesized in the choroid plexus rather than liver-derived circulating TTR protein such that patisiran and inotersen are ineffective at preventing neurological disease progression which carries a poor prognosis." (PMID 36741843, 2022). "Among the affected genes after OGD/R in human cerebral organoids, transthyretin (TTR), alpha-2-HS-glycoprotein (AHSG), and fibrinogen gamma chain (FGG) were found to be related to neurological disease." (PMID 34168538, 2021). "In particular, we looked at modifications induced by S-sulfhydration in the cerebral transthyretin (TTR), which are already known to be correlated with some neurological diseases such as MS and AD." (PMID 33800163, 2021). "Transthyretin (TTR) stabilizers: The safety and efficacy of tafamidis in delaying neurologic disease progression in patients with early-stage ATTRv-PN (stage 1) have been demonstrated in several clinical trials, extension studies, and around 10 years of clinical follow-up." (PMID 37376074, 2023). "Irrespective of this concomitant TTR tetramer stabilizer use, patisiran was shown to have a similar effect on mNIS+7; notably, the 6 patients who discontinued their stabilizer within 18 months did not exhibit neurologic disease progression." (PMID 32641071, 2020).
genetic disorder (26 papers, 2014 to 2026). "Hereditary transthyretin amyloidosis (ATTRv) is a rare genetic disorder caused by mutations in the TTR gene." (PMID 40260709, 2025). "Inotersen (Tegsedi) is a 20-mer PS ASO gapmer that was approved in 2018 for the treatment of hereditary transthyretin-mediated amyloidosis (hATTR), a rare genetic disorder that causes misfolding of transthyretin (TTR) protein." (PMID 41394159, 2025). "Hereditary transthyretin amyloidosis (ATTR) is an autosomal dominant, life-threatening genetic disorder caused by a single-nucleotide variant in the transthyretin gene." (PMID 39044869, 2024). "Patisiran targets and degrades both mutant variant and wild-type transthyretin (TTR) mRNA, ameliorating the symptoms of this rare genetic disease." (PMID 35326738, 2022). "As more of the population uses direct-to-consumer DNA testing that includes screening for genetic diseases, more people will be made aware that they are carriers of variant TTR." (PMID 35414857, 2022). "Hereditary transthyretin amyloidosis (hATTR) is an uncommon multisystem genetic disorder caused by deposition of misfolded mutant transthyretin (TTR) protein in multiple organs." (PMID 35751086, 2022). "TTR-FAP (OMIM: 176300) is a rare genetic disorder caused by mutations of the TTR gene in chromosome 18q12." (PMID 26437390, 2015). "The majority of circulating TTR is produced in the liver and the holy grail in the treatment of hATTR (and many other genetic disease) would be to correct the genetic error at a somatic (or DNA) level, meaning that ongoing treatments would not be required." (PMID 35596796, 2022). "Numerous techniques, including a single-cell PGD use for the detection of the c.148G>A (p.V50M) mutation in the TTR gene, have been developed and applied to performing PGD for many rare genetic disorders, and the number of cycles increases each year." (PMID 31018485, 2019). "In this genetic disorder, Transthyretin accumulates preferentially in the extracellular matrix of peripheral and autonomic nervous systems leading to cell death and dysfunction." (PMID 25519307, 2014). "ATTR is particularly suited to this treatment as unlike other dominant genetic diseases, the most effective treatment requires full suppression of both wild-type and mutant TTR." (PMID 35596796, 2022).
cardiovascular diseases (16 papers, 2011 to 2025). "Numerous studies have shown that low levels of TTR are associated with increased mortality overall and in relation to cardiovascular disease and several malignancies." (PMID 40717228, 2025). "Low TTR levels are generally observed in cardiovascular disorders, particularly disorders associated with T2DM and/or calcification." (PMID 34359938, 2021). "Many of the identified proteins are known markers, risk factors, or proteins known to be involved in cardiovascular disease; e.g. transthyretin, apoA1, fibrinogen, serum amyloid A protein, haptoglobin, plasminogen, and others." (PMID 21631938, 2011). "The risk of cardiovascular disease increased by 14% per SD decrease in TTR levels." (PMID 39043640, 2024). "Over the follow-up period, individuals with high and low TTR levels had 1,458 (9.3%) and 1,622 (10.3%) events of cardiovascular disease, respectively." (PMID 39043640, 2024). "Here, the authors present the clinical correlates of transthyretin levels and show that reduced TTR levels are associated with an increase risk of cardiovascular disease and mortality." (PMID 39043640, 2024). "The incidence rate of cardiovascular disease was 7.19 (95% CI: 6.83–7.57) per 1000 person-years in individuals with high TTR levels and 8.12 (95% CI: 7.73–8.53) per 1000 person-years in individuals with low TTR levels." (PMID 39043640, 2024). "The involvement of TTR in osteoarticular disorders is an indirect indication of TTR involvement in calcification occurring in cardiovascular disease." (PMID 34359938, 2021). "The roles of TTR in biomineralization, calcification, and osteoarticular and cardiovascular diseases are broadly discussed." (PMID 34359938, 2021). "In agreement with the association between low circulating levels of transthyretin and cardiovascular disease, we detected lower expression of transthyretin in exosomes of STEMI than in those of CCS patients." (PMID 34360827, 2021). "Lower TTR levels were linked with higher mortality in the general elderly population (potentially confounded by the correlation of TTR levels with nutritional status), several oncological diseases, respiratory diseases, as well as cardiovascular diseases, and ATTR." (PMID 40717228, 2025). "TTR likely serves as a key regulator of cerebrovascular and cardiovascular diseases." (PMID 40717228, 2025). "Cardiovascular diseases are also accompanied by the reduction of negative acute phase reactants such as albumin, transferrin, transthyretin, retinol-binding protein, antithrombin, and transcortin." (PMID 24049653, 2012). "Cardiovascular disease is also accompanied by the reduction of negative acute phase reactants such as albumin, transferrin, transthyretin, retinol-binding protein, antithrombin, and transcortin." (PMID 24049653, 2012).
metabolic disorders (6 papers, 2022 to 2025). "Thus, the marked loss of TTR in obese adiposomes mirrors its systemic decline in metabolic disease, potentially exacerbating the disruption of metabolic and vascular homeostasis." (PMID 40981199, 2025). "It is currently unknown whether patients with ATTR have abnormal glucose homeostasis driven by a deficiency in TTR and are, therefore, at a higher risk of developing diabetes and other metabolic diseases." (PMID 40717228, 2025).
peripheral nerve disease (5 papers, 2019 to 2022). "In 2018, the first siRNA drug Onpattro (aka Patisiran), which targets transthyretin (Ttr) gene for the treatment of peripheral nerve disease in adults was approved by the U.S. Food and Drug Administration (FDA)." (PMID 36045375, 2022). "In August 2018, the first siRNA-related therapy, patisiran, was approved by the FDA for the treatment of peripheral nerve disease by targeting an abnormal form of the transthyretin (TTR) gene." (PMID 30906315, 2019).
benign tumors (4 papers, 2018 to 2024). "In conclusion, the urinary biomarker panel with HE4, creatinine, CEA, and TTR provided promising efficacy in predicting OC over benign tumors in women with pelvic masses." (PMID 31590408, 2019). "A multimarker panel consisting of HE4, creatinine, CEA, and TTR presented the best performance with 93.7% sensitivity (SN) at 70.6% specificity (SP) to predict OC over the benign tumor." (PMID 31590408, 2019). "HE4 is the most influential biomarker in the differential diagnosis between OC and benign tumors, followed by creatinine, CEA, NCAM, and TTR." (PMID 31590408, 2019).
adenocarcinoma (2 papers, 2021 to 2022). A common cancer characterized by the presence of malignant glandular cells. "Apolipoprotein A-IV (APOA4) and Transthyretin (TTR), which were included in random forest classifiers, were both described to be dysregulated in adenocarcinoma before." (PMID 36232544, 2022).
central nervous system disorder (2 papers, 2012 to 2025). A disease involving the central nervous system. "TTR involvement in various central nervous system disorders, diabetes melitus, preclampsia has been described." (PMID 22630135, 2012). "Studies have found that patients with the highly amyloidogenic and unstable TTR variant (TTR D18G) do not show severe systemic pathological manifestations, presenting only with late-onset central nervous system disorders." (PMID 40666113, 2025).
CNS tumors (1 paper, 2015). "A total of 26 CSF proteins were identified as candidate biomarkers for neurological or psychological diseases or CNS tumors by IPA analysis, and the median inter-individual CV of these proteins was 0.177; only TTR and CHI3L1 had CVs slightly higher than 0.3." (PMID 26222143, 2015).
immune dysfunction (1 paper, 2025). "The structure and function of CP are impaired in AD, resulting in secretory, transport, and immune dysfunction and reduced transthyretin (TTR) secretions, causing decreased Aβ clearance." (PMID 41013670, 2025).
TTR also shares sentences with these, for which no sentence is quoted: Fabry disease (12 papers); Acute hepatic porphyria (9); Duchenne muscular dystrophy (6); Hypercholesterolemia (6); prion disease (6); cardiac sarcoidosis (5); glomerulonephritis (5); Huntington disease (5); primary hyperoxaluria type 1 (5); acute myocardial infarction (4); Cachexia (4); glioblastoma (4); hereditary angioedema (4); Ataxia (3); cataract (3); coccidioidomycosis (3); diastolic heart failure (3); gastrointestinal disorder (3); hypertrophy (3); Parkinson (3); Pleural effusion (3); primary hyperoxaluria (3); primary Sjögren's syndrome (3); psychosis (3); Renal amyloidosis (3); sarcoidosis (3); amaurosis fugax (2); anterior uveitis (2); brain diseases (2); cardiac arrhythmia (2).
A further 201 diseases each share a sentence with TTR in 2 papers or fewer.